MBP (myelin basic protein)
Diseases named in the same sentence as MBP in open-access papers (continued):
Sharing a sentence is not in itself a finding about the gene and the disease.
multiple sclerosis (continued). "However, since anti-MBP antibodies have already been described in several other diseases such as multiple sclerosis, Parkinson's disease, rheumatoid arthritis or schizophrenia, it seems unlikely that they would be useful as specific biomarkers for the diagnosis of ASD." (PMID 31379804, 2019). "Furthermore, it was shown that HSP70 could directly bind MBP, both in vitro and in autopsy white matter tissue from multiple sclerosis patients, which also parallels our observation of both proteins being decreased in optic nerve tissue after TBI." (PMID 27088355, 2016). "At week 5, significantly reduced MBP levels in the CPZ group confirmed effective demyelination, consistent with prior reports using cuprizone to model multiple sclerosis-like pathology." (PMID 41155593, 2025). "In the case of multiple sclerosis (MS), the superoxide (from NOX2) generates oxidative damage to myelin basic protein (MBP), and it is oxidative damage that leads to demyelination and axonal injury." (PMID 40806624, 2025). "MOG and MBP peptides are used in EAE induction because multiple sclerosis patients have high levels of anti-MOG and anti-MBP antibodies, justifying the use of these factors for EAE induction in animal models." (PMID 39000105, 2024). "In the multiple sclerosis mouse model of experimental allergic encephalomyelitis (EAE), myelin basic protein (MBP) activated human Treg cells control the expression of T-effector cells with enhanced Foxp3 expression." (PMID 35720406, 2022). "The myelin proteome found to be implicated in multiple sclerosis disease are myelin basic protein (MBP), myelin oligodentrocyte glycoprotein (MOC), and proteolipid protein (PLP); these are targets for multiple sclerosis treatments." (PMID 35447967, 2022). "Ectopic hepatic expression of myelin basic protein (MBP), a human autoantigen in multiple sclerosis (MS), protected mice from the induction of MS-like disease in the CNS by generation of MBP-specific Treg that blocked autoaggressive T cells." (PMID 35903109, 2022). "An example is the development of immunoregulators (epitope peptides of MBP and MOG) for Multiple Sclerosis, which serve as platforms for the design, synthesis, and development of MS therapeutics and vaccines." (PMID 35447967, 2022). "Analysis of the pH-dependence of the MBP-hydrolyzing activity of abzymes in SLE, multiple sclerosis, and schizophrenia showed high heterogeneity of the pH optimum and individual variability for each patient." (PMID 35806400, 2022). "Intrinsically disordered myelin basic protein (MBP) is one of the key autoantigens in autoimmune neurodegeneration and multiple sclerosis particularly." (PMID 34827627, 2021). "In order to confirm the effects of STX564 in non-transformed T cells, we employed rat T cells reactive for myelin basic protein (TMBP cells), known to induce experimental autoimmune encephalomyelitis (EAE), a model for multiple sclerosis." (PMID 33581218, 2021). "Recently, in the context of neurons and multiple sclerosis, beyond neuro-filaments (NEF-L and NEF-H), MBP and GFAP, more than 20 new cytoskeletal proteins (tubulin, gelsolin, etc.)were also identified as deiminated." (PMID 33228136, 2020). "In a similar study, it was also shown that progesterone upregulates the expression of MBP, PLP, Nkx 2.2, and Olig1 in the spinal cord of a murine model of multiple sclerosis." (PMID 32295179, 2020). "Top hits representing skin and/or joint disease (PsA probands vs. controls) included a 14% hypermethylated DMR spanning the promoter and body of myelin basic protein (MBP), an autoantigen in multiple sclerosis." (PMID 30779748, 2019). "This breakdown allows the activation of MBP-specific CD8 lymphocytes, leading to multiple sclerosis, an inflammatory disease affecting the brain and spinal cord." (PMID 31001336, 2019). "Among the myelin antigens, the major target of multiple sclerosis (MS) and experimental autoimmune encephalomyelitis (EAE) is the myelin basic protein (MBP)." (PMID 25405025, 2014).
multiple sclerosis (continued). "A meta-analysis of 33 animal studies showed that administration of MBP reduced the severity of EAE, which is an animal model for multiple sclerosis." (PMID 23874156, 2013). "GA was synthesized to resemble the structure of myelin basic protein (MBP), one of the major components involved in EAE and multiple sclerosis but instead of inducing the disease, it was found to be protective." (PMID 19250545, 2009). "While MBP, a structural component of central nervous system (CNS) myelin, correlates with disease severity in demyelinating disorders, it lacks specificity for GBS, as elevations are also documented in multiple sclerosis (MS)." (PMID 40386770, 2025). "For example, a peptide approach identified epitopes in myelin oligodendrocyte glycoprotein (MOG) and myelin basic protein (MBP) in patients with multiple sclerosis proteins, but these proteins were not identified using the Human ProtoArray." (PMID 36690876, 2023). "For example, antibodies from the plasma of patients with systemic lupus erythematosus (SLE) and multiple sclerosis (MS) were found to hydrolyze four oligopeptides corresponding to epitopes of myelin basic protein (MBP), but not short tri- and tetrapeptides." (PMID 37766170, 2023). "Recent data indicate that significantly elevated levels of (nonhybrid) isoaspartic residues can be detected in myelin basic protein obtained from brain tissue of organ donors with multiple sclerosis." (PMID 37734557, 2023). "however, found no “increase in the risk of clinically definite multiple sclerosis or of multiple sclerosis according to the McDonald criteria among patients who were positive for anti-MOG antibodies, anti-MBP antibodies, or both”." (PMID 34889995, 2022). "Polyreactive IgGs-abzymes against MBP, five histones, and DNA with extended cytotoxicity can play a very negative role in the pathogenesis of multiple sclerosis and probably other different diseases." (PMID 36009424, 2022). "The specific ABZs against MBP can assault and hydrolyze the MBP of the myelin sheath of axons, possessing an essential negative role in the multiple sclerosis pathogenesis due to the infringement of nerve impulse conduction." (PMID 36289924, 2022). "Work in multiple sclerosis models also supports negative effects of GCs on MBP expression and white matter." (PMID 33642975, 2021). "Reports from four different groups showed that feeding autoantigens such as collagen and myelin basic protein (MBP) could prevent the development of experimental models of arthritis and multiple sclerosis respectively." (PMID 35919733, 2021). "Thereafter, abundant proteins, such as myelin basic protein (MBP), fibrin, vimentin and GFAP, were also demonstrated to be targets of this post-translational modification, in several pathological contexts, such as multiple sclerosis, rheumatoid arthritis and Alzheimer’s disease." (PMID 33228136, 2020). "Several central nervous system (CNS) proteins are associated with disease and are either known or potential targets for cysteine cathepsins, including amyloid beta and Tau (Alzheimer’s disease), alpha-synuclein (Parkinson’s disease), and myelin basic protein (MBP, multiple sclerosis)." (PMID 31569504, 2019). "Gene regions spanning the identified four-SNP signature, HLA-DQB2, MBP, UVRAG, and ZAK(CDCA7), are known to be related to either the MoA of Copaxone or the pathophysiology of multiple sclerosis: HLA-DQB2 is involved in antigen processing and presentation, central to Copaxone’s MoA." (PMID 28569182, 2017). "Dendritic cells (DCs) rendered suppressive by treatment with mitomycin C and loaded with the autoantigen myelin basic protein demonstrated earlier their ability to prevent experimental autoimmune encephalomyelitis (EAE), the animal model for multiple sclerosis (MS)." (PMID 27131971, 2016).
multiple sclerosis (continued). "Similarly, the liver-specific ectopic expression of myelin basic protein (MBP), a major oligodendrocyte autoantigen in multiple sclerosis (MS), resulted in the protection from neuroinflammatory disease in a mouse model for MS." (PMID 27916939, 2016). "Formation of Schiff's bases between the secosterols and myelin basic protein (MBP) induces myelin instability and might contribute to the onset and progression of multiple sclerosis." (PMID 27042259, 2016). "The amino-terminal domain of TyrRS (1 nM) has been reported to induce PMN migration, and human myelin basic protein (10–30 μg/ml) has been reported to induce a dose-dependent release of interferon-γ, TNF-α and IL-10 from the mononuclear cells of patients with multiple sclerosis." (PMID 25915936, 2015). "Chronic demyelinated multiple sclerosis lesions contain oligodendrocyte precursor cells (OPCs) with Mbp mRNA but no MBP protein." (PMID 26379499, 2015). "Such reactions can also be induced against autoantigen, for example to myelin basic protein (MBP) in rats with experimental autoimmune encephalomyelitis induced with MBP, an animal model for multiple sclerosis.Here we demonstrate how to induce an adoptive DTH reaction in Lewis rats." (PMID 19252470, 2007). "They suppressed cell proliferation and down-regulated myelin basic protein (MBP)-induced activation of Akt and NF-κB, production of TNF-α, and expression of activation markers such as COX-2, altogether supporting the potential of these compounds in the therapy of multiple sclerosis." (PMID 36551756, 2022). "Previously, we showed that myelin-reactive autoantibodies from patients with multiple sclerosis (MS) and mice with experimental autoimmune encephalomyelitis (EAE) exhibit the ability to recognize and hydrolyse distinct epitopes within myelin basic protein (MBP)." (PMID 30139963, 2018). "MBP normally contains non-citrullinated arginine residues allowing compact myelin sheaths to form; citrullinated MBP is not capable of forming tight sheaths which is hypothesized to lead to neurodegeneration and possibly multiple sclerosis." (PMID 20668670, 2010). "For example, an N‐terminally acetylated MHC class II epitope derived from myelin basic protein (MBP) can elicit experimental autoimmune encephalomyelitis, a mouse model of multiple sclerosis, whereas the nonacetylated form cannot." (PMID 39609891, 2025). "Abzymes specifically hydrolyze myelin basic protein (MBP), but not other control proteins revealed in the blood of patients with multiple sclerosis (MS), systemic lupus erythematosus (SLE), and schizophrenia." (PMID 33143355, 2020). "IgGs from patients with multiple sclerosis and systemic lupus erythematosus (SLE) purified on MBP-Sepharose in contrast to canonical proteases hydrolyze effectively only myelin basic protein (MBP), but not many other tested proteins." (PMID 23520443, 2013). "Interestingly, the capacity to cleave myelin basic protein has also been attributed to KLK13, but has not been related to the pathogenesis of multiple sclerosis." (PMID 32655372, 2020).
experimental autoimmune encephalomyelitis (101 papers, 2007 to 2025). An autoimmune demyelinating disease of the central nervous system that is produced experimentally in animals by the injection of homogenized brain or spinal cord in Freund's adjuvant. "Another study observed that myelin basic protein (MBP)-specific Th2 cells can cause experimental autoimmune encephalomyelitis (EAE), but only in association with T-cell immunodeficiency in RAG-1-deficient mice." (PMID 35894054, 2022). "Intraperitoneal injection of NMO-IgGs induced astrocyte injury associated with complement deposition in rat models of experimental autoimmune encephalomyelitis (EAE) immunized with myelin basic protein (MBP), which established the pathogenicity of anti-AQP4 antibodies." (PMID 39125739, 2024). "The HLA-II-Tg mice studies showing that HLA-DRB1*1501-Tg mice are susceptible to myelin basic protein (MBP)- or myelin oligodendrocyte glycoprotein (MOG)-induced experimental autoimmune encephalomyelitis (EAE) are also consistent with the primary contribution of DRB1*1501 to MS pathogenesis." (PMID 25360418, 2014). "Substantial differences in the degradation pattern of this neuroantigen were found, which could indicate the better presentation MBP parts on MHC molecules in the case of mice predisposed to the development of experimental autoimmune encephalomyelitis." (PMID 22649589, 2009). "Early studies implicated MBP in the pathogenesis of MS, as adoptive transfer of MBP-reactive T cells is sufficient to induce experimental autoimmune encephalomyelitis (EAE), the standard animal model of MS." (PMID 41226806, 2025). "For instance, anti-MBP antibodies induced by ATAbs can exacerbate demyelination, as demonstrated in experimental autoimmune encephalomyelitis (EAE) models." (PMID 40933045, 2025). "Anti-B7-1 immunoglobulin (Ig) promoted Th2 differentiation in naïve MBP-specific Th precursor cells and mitigated experimental autoimmune encephalomyelitis (EAE)." (PMID 39000519, 2024). "Recently, an in vitro study showed that myelin basic protein (MBP)-CAART has higher cytotoxic activity against autoreactive B cells in experimental autoimmune encephalomyelitis (EAE)." (PMID 38673811, 2024). "IgGs against five individual histones (H2B, H1, H2A, H3, and H4) and MBP were isolated from the blood of experimental autoimmune encephalomyelitis-prone C57BL/6 mice by affinity chromatography." (PMID 37049736, 2023). "IgGs against individual histones (H2A, H1, H2B, H3, and H4) and MBP were isolated from the blood of experimental-autoimmune-encephalomyelitis-prone C57BL/6 mice by several affinity chromatographies." (PMID 37239982, 2023). "Expansion in vitro of myelin basic protein (MBP)-reactive CD4+CD25+ Tregs from donor TCR transgenic mice was able to protect from experimental autoimmune encephalomyelitis." (PMID 35740942, 2022). "In a similar way, simultaneous injection of OVA and myelin basic protein (MBP) prevents experimental autoimmune encephalomyelitis (EAE) in mice orally tolerant to OVA." (PMID 35170683, 2022). "As in human MS, experimental autoimmune encephalomyelitis (EAE) in mice is also characterized by demyelinating inflammation induced by immunization with antigens (such as myelin basic protein-MBP) which serves an equivalent analogy." (PMID 36032110, 2022). "PLP and MBP are the two most abundant myelin proteins of the myelin sheath and their importance for inducing experimental autoimmune encephalomyelitis (EAE), one mouse model for MS, has been previously discussed." (PMID 33810144, 2021). "Our laboratory has designed analogues of Ac1-9, the N-terminal epitope of myelin basic protein (MBP) that induces experimental autoimmune encephalomyelitis (EAE) in H-2u mice." (PMID 33878516, 2021). "GA initially was developed at the Weizmann Institute in Israel as a chemical and immunological analog of the major myelin antigen, myelin basic protein (MBP), to induce experimental autoimmune encephalomyelitis (EAE)." (PMID 31354720, 2019).
experimental autoimmune encephalomyelitis (continued). "We used myelin basic protein (MBP)-proteolipid protein (PLP)-induced experimental autoimmune encephalomyelitis (EAE) in C57BL/6 (B6) mice as B cell-dependent model of MS." (PMID 30098594, 2018). "This particular rat model is carried out in a Lewis rat on a background of experimental autoimmune encephalomyelitis (EAE) using T cells reactive to myelin basic protein, in this case, generated by direct immunization." (PMID 30648122, 2018). "Experimental autoimmune encephalomyelitis was induced by myelin basic protein in complete Freud Adjuvant in the footpads of DA and AO rats." (PMID 26092157, 2015). "The experimental autoimmune encephalomyelitis (EAE) rat model of human MS shows a selective upregulation of the OX40 protein in encephalitogenic myelin basic protein-specific T cells in the spinal cord during onset of the disease." (PMID 23651542, 2013). "Our group has previously studied this in the MS-like model experimental autoimmune encephalomyelitis (EAE) after immunization with myelin basic protein (MBP)." (PMID 22586495, 2012). "The MBP digest fragments comprised the known immunogenic sequence regions of MBP, MBP84-104, and MBP68-86 sequences, capable of causing experimental autoimmune encephalomyelitis or neuritis in animal models." (PMID 22676642, 2012). "Matrix metalloproteinases (MMPs) play a significant role in the fragmentation of myelin basic protein (MBP) and demyelination leading to autoimmune multiple sclerosis (MS) and experimental autoimmune encephalomyelitis (EAE)." (PMID 19300513, 2009). "There have also been reports of anti-citrullinated-MBP T cell reactivity in MS, as well as evidence that citrullinated MBP can serve as an autoantigen in experimental autoimmune encephalomyelitis (EAE)." (PMID 18826638, 2008). "In situ hybridization analysis of LPS/IFNg and experimental autoimmune encephalomyelitis (EAE)–induced CNS inflammation revealed that only a subset of CNS macrophages express Golli-MBP." (PMID 17982583, 2007). "B10.PL mice dually transgenic (Tg) for beta-actin promoter-driven SRG3 (SRG3β-actin Tg) and a myelin basic protein (MBP)-specific T cell receptor (TCR) are partially protected against experimental autoimmune encephalomyelitis (EAE) compared with MBP TCR Tg B10.PL mice." (PMID 39519233, 2024). "In addition, EBNA1 amino acids 411 to 426 and myelin basic protein cross-reactivity has been demonstrated in experimental autoimmune encephalomyelitis (EAE), and EBNA1-specific T cells have been shown to react to a mixed myelin antigen pool." (PMID 37196088, 2023). "OAL in combination with myelin basic protein suppresses experimental autoimmune encephalomyelitis." (PMID 36969154, 2023). "Moreover, an increase of phosphorylated JNK (p-JNK) was found in the spinal cords of myelin basic protein (MBP) experimental autoimmune encephalomyelitis (EAE) Lewis rats during the acute phase of the disease." (PMID 32977663, 2020). "Furthermore, activation of MBP-specific T cells by SLPA upon active immunization induced experimental autoimmune encephalomyelitis (EAE) in MBP-TCR/DR2a Tg mice." (PMID 33374217, 2020). "Studies using animal models confirmed the essential role of one of the major components of the myelin sheath, the myelin basic protein (MBP), in MS pathogenesis, as transfer of MBP-sensitized T cells induced experimental autoimmune encephalomyelitis (EAE), a disease in mice similar to MS." (PMID 29085375, 2017). "Recently, immunodominant MBP peptides encapsulated into the mannosylated liposomes, referred as Xemys, were shown to suppress development of experimental autoimmune encephalomyelitis, a rodent model of MS, and furthermore passed the initial stage of clinical trials." (PMID 29085375, 2017). "Moreover, the MBP peptide 1–9 induced regulatory T cells of the Tr1 type in vivo, and neutralization of IL-10 prevented the peptide MBP from protecting against experimental autoimmune encephalomyelitis." (PMID 28455817, 2017).